SCN10A (sodium voltage-gated channel alpha subunit 10)
Description:
Tetrodotoxin-resistant channel that mediates the voltage-dependent sodium ion permeability of excitable membranes. Assuming opened or closed conformations in response to the voltage difference across the membrane, the protein forms a sodium-selective channel through which sodium ions may pass in accordance with their electrochemical gradient. Plays a role in neuropathic pain mechanisms.
Synonyms: PN3; hPN3; Nav1.8; SNS; FEPS2
Tractability: Small molecule: an approved drug acts on it; a structure with a bound ligand is known; a high-quality ligand is known; it belongs to a druggable protein family. Antibody: its Gene Ontology location is reachable by antibodies, with high confidence; UniProt places it where antibodies can reach, with medium confidence; UniProt predicts a signal peptide or a membrane-spanning region. PROTAC: UniProt records ubiquitination sites on it; ubiquitination databases record sites on it; a small molecule that binds it is known.
Target class: Voltage-gated ion channel; Voltage-gated sodium channel; Ion channel
Chemical probes: A-803467, suzetrigine (high quality)
Safety:
Unwanted effects reported when the protein is acted on. In parentheses: how it was acted on, where the effect was seen, and who reports it.
gastrointestinal toxicity (source: ClinPGx)
Gene: Protein-coding gene on chromosome 3 (38,696,802 to 38,816,286, reverse strand). Ensembl gene ENSG00000185313.
Subcellular location: Cell membrane
Subcellular location (Human Protein Atlas): Connecting piece; Flagellar centriole
Pathways (Reactome):
Developmental Biology: Interaction between L1 and Ankyrins
Muscle contraction: Phase 0 - rapid depolarisation
Gene Ontology:
Molecular function: transmembrane transporter binding; voltage-gated sodium channel activity; monoatomic cation channel activity; monoatomic ion channel activity; voltage-gated monoatomic ion channel activity involved in regulation of presynaptic membrane potential
Biological process: AV node cell action potential; bundle of His cell action potential; membrane depolarization during action potential; regulation of atrial cardiac muscle cell membrane depolarization; regulation of cardiac muscle contraction; regulation of heart rate; regulation of monoatomic ion transmembrane transport; sodium ion transmembrane transport; cardiac muscle cell action potential involved in contraction; sensory perception; behavioral response to pain; circadian rhythm; detection of mechanical stimulus involved in sensory perception; detection of temperature stimulus involved in sensory perception of pain; monoatomic ion transport; odontogenesis of dentin-containing tooth; regulation of presynaptic membrane potential; sodium ion transport; transmembrane transport
Cellular component: extracellular exosome; plasma membrane; voltage-gated sodium channel complex; axon; C-fiber; clathrin complex; glutamatergic synapse; membrane; presynaptic membrane
Genetic constraint (gnomAD): Loss-of-function variants: 152 observed, 164.32 expected, observed/expected ratio (o/e) 0.93, 90% interval 0.81 to 1.06. The upper end of that interval is the gene's LOEUF score, 1.06, which puts it in group 4 of 6, group 1 being the genes least tolerant of losing a copy. Missense variants: 2,448 observed, 2,470.2 expected, observed/expected ratio (o/e) 0.99, 90% interval 0.96 to 1.02. Synonymous variants: 956 observed, 922.39 expected, observed/expected ratio (o/e) 1.04, 90% interval 0.98 to 1.09.
Gene-disease validity (ClinGen):
ClinGen rates the evidence that SCN10A causes each of these diseases.
Brugada syndrome (autosomal dominant): Disputed. A genetically heterogeneous condition characterized by complete or incomplete right bundle branch block accompanied by ST elevation in leads V1-V3.
Homologues: Orthologues: chimpanzee SCN10A (99% identical), macaque SCN10A (98% identical), dog SCN10A (88% identical), pig SCN10A (86% identical), guinea pig SCN10A (84% identical), rat Scn10a (83% identical), mouse Scn10a (82% identical), rabbit SCN10A (77% identical), zebrafish scn5lab (57% identical), zebrafish scn12aa (56% identical). Paralogues in human: SCN5A (62% identical), SCN2A (58% identical), SCN3A (58% identical), SCN1A (57% identical), SCN8A (57% identical), SCN9A (56% identical), SCN4A (54% identical), SCN11A (49% identical), SCN7A (39% identical), CACNA1A (23% identical), CACNA1S (23% identical), CACNA1C (23% identical), and 14 more.
Diseases named in the same sentence as SCN10A in open-access papers:
SCN10A is named in the same sentence as 121 diseases in open-access papers, as found by Europe PMC text mining. Sharing a sentence is not in itself a finding about the gene and the disease. The quoted sentences say what the papers report.
Arrhythmia (28 papers, 2013 to 2026). Any cardiac rhythm other than the normal sinus rhythm. "Genome-wide association studies indicate that mutations in the SCN10A gene (NaV1.8) are associated with increased risk for arrhythmias, Brugada syndrome, and sudden cardiac death." (PMID 37373335, 2023). "Variants in the SCN10A gene (NaV1.8) were shown to be associated with cardiac arrhythmias such as atrial fibrillation and sudden cardiac death." (PMID 37373335, 2023). "The ion channel genes SCN5A/SCN10A locus is another hotspot heavily loaded with variants linked to cardiac arrhythmia and conduction system disorders." (PMID 33777110, 2021). "One cardiac arrhythmia-associated SNP rs6801957 is located within the intron of SCN10A but is encompassed by a human-mouse conserved enhancer that interacts with the nearby gene SCN5A." (PMID 33777110, 2021). "Individual III-4, who died suddenly despite a normal cardiac function, carried LPVs in the AKAP9 and SCN10A genes, both implicated in cardiac arrhythmias." (PMID 34790974, 2021). "Certain genome-wide association studies reported an association of SCN10A with changes in ECG parameters but most importantly with cardiac arrhythmias such as atrial fibrillation and sudden cardiac death." (PMID 34782600, 2021). "Due to sodium channel mutations in the cardiac membrane, most commonly SCN5A and SCN10A, the heart can be triggered into a fatal arrhythmia." (PMID 32550094, 2020). "While SCN5A variants are well-known to be associated with cardiac arrhythmias, the identification of SCN10A as a major risk region for ECG traits was intriguing." (PMID 33202810, 2020). "Several studies have indicated a potential role for SCN10A/NaV1.8 in modulating cardiac electrophysiology and arrhythmia susceptibility." (PMID 31916131, 2019). "Genetic variants at the SCN5A, HEY2, and SCN10A loci have been associated with arrhythmia occurrence in independent studies." (PMID 27200363, 2016). "Previous studies suggested that SCN10A/Nav1.8 may influence cardiac electrophysiology and the susceptibility to cardiac arrhythmias." (PMID 40182425, 2025). "However, genome-wide association studies reported that the SCN10A gene is associated with cardiac arrhythmias." (PMID 38892333, 2024). "The results suggested that RYR2-A1855D and SCN10A-1362H double variants may increase the susceptibility of cardiomyocytes to arrhythmias." (PMID 37122207, 2023). "However, a better understanding of the mechanisms explaining how dysregulation of SCN5A and/or SCN10A expression is linked to alterations in ECGs and cardiac arrhythmias is still missing." (PMID 33202810, 2020). "These recent findings suggest that rs6801957 is the causal SNP and that this SNP may modulate SCN5A and / or SCN10A expression levels in human heart and thereby impact on conduction and arrhythmia risk." (PMID 23437344, 2013). "Eight of these (50.0%) carried additional variants in other genes, including KCNJ8, SCN5A, SCN10A, ABCC9, and other genes related to inherited arrhythmias." (PMID 34222376, 2021). "The family member had PVs and LPVs in 7 genes implicated in hereditary cardiomyopathies and/or cardiac arrhythmias, including LPVs in SCN10A and AKAP9, which are implicated in cardiac arrhythmias." (PMID 34790974, 2021). "Interestingly, some known SCN10A variants have been reported to modulate cardiac SCN5A expression, influencing cardiac physiology and factors that predispose individuals to arrhythmia." (PMID 35629146, 2022). "Interestingly, polymorphism of the Nav1.8 encoding gene SCN10A was linked to modulation of heart rate and myocardial conduction as well as arrhythmias." (PMID 35215342, 2022). "Prior studies report protective variants against arrhythmia in the coding regions of the KCNQ1 and SCN5A genes and protective variants against Brugada syndrome in a coding region of the SCN10A gene and in a non-coding site downstream the HEY2 gene in the Japanese population." (PMID 33948580, 2021).
Arrhythmia (continued). "The modifier roles of the PVs or LPVs in the PKP2, DSP, SCN10A, and others identified in the family members benefit from biological plausibility and the well-established roles of these genes in cardiomyopathies and/or arrhythmias." (PMID 34790974, 2021). "SCN10A/NaV1.8 is correlated with cardiac conduction and arrhythmia." (PMID 32848771, 2020). "In parallel, 902 arrhythmia-related genes were retrieved, yielding 24 overlapping targets, among which five hub genes (PIK3CA, CREBBP, NR3C1, SCN10A, and KCNA5) were identified." (PMID 42292832, 2026). "We further analyzed potential triggers of arrhythmias and found reduced delayed afterdepolarizations (DAD) in SCN10A-KO iPSC-CM and after the specific inhibition of NaV1.8 in control cells." (PMID 38892333, 2024). "SCN10A, SCN5A, and CAV1 have roles in cardiac conduction and arrhythmia." (PMID 39540287, 2024). "Prior to the GWAS linking SCN10A to cardiac arrhythmias, no cardiac function of SCN10A had been described, and expression of SCN10A in the heart had not been detected." (PMID 38201209, 2023).
Brugada syndrome (20 papers, 2015 to 2025). "Many GWAS involving SCN5A typically also find consistent associations between variants in and around the neighboring gene SCN10A and conduction parameters and Brugada syndrome." (PMID 38201209, 2023). "Another case report detected a pathogenic variant in the SCN10A gene, a gene associated with Brugada syndrome, in a three-month-old male infant who had died of SUID." (PMID 35003713, 2021). "An intronic enhancer in the SCN10A gene carries a cluster of GWAS hits associated with Brugada syndrome." (PMID 33948580, 2021). "SCN10A variants have also been associated with atrial fibrillation (AF) and with Brugada syndrome, an inherited cardiac disease characterized by cardiac conduction slowing and increased risk for SCD." (PMID 31916131, 2019). "Mutations or variants in SCN10A (associated with both gain and loss of Nav1.8-based sodium channel function) have been associated with inherited arrhythmia syndromes such as Brugada syndrome, as well as increased AF susceptibility." (PMID 31916131, 2019). "For examples, while gain-of-function mutations of SCN10A cause painful peripheral neuropathy, its loss-of-function mutations result in prolonged cardiac conduction disease and Brugada syndrome or KSD." (PMID 29992996, 2018). "While SCN5A is the primary cause of Brugada syndrome, rare SCN10A variants have been found in about 16% of SCN5A-negative Brugada patients." (PMID 27446933, 2016). "In addition, variants in SCN10A, the alpha subunit encoding Nav1.8, which is found mainly in nociceptive neurons in the dorsal root ganglia and visceral neurons in the heart, have been shown to be associated with atrial fibrillation and Brugada syndrome." (PMID 36975511, 2023). "Recent studies have identified three common genetic variants associated with Brugada syndrome (BrS) near the genes SCN5A, SCN10A, and HEY2." (PMID 40338408, 2025). "Interestingly, we observed that only 2 pan-blocks accumulate GWAS hits associated with Brugada syndrome and common SNVs associated with SCN5A or SCN10A expression (proximal and distal SNV subsets)." (PMID 33948580, 2021). "At this point, there exist no clinically observed variants in SCN10A that can be classified as pathogenic, and therefore we cannot be certain that pathogenic variants in SCN10A cause Brugada syndrome." (PMID 27446933, 2016). "Moreover, rs6801957 (tagging the entire haplotype with all ECG-trait- and Brugada-syndrome-associated SNPs in LD) showed a cis-eQTL effect on SCN10A expression, not SCN5A expression, in atrial and ventricular tissue, consistent with the findings in the other two reports." (PMID 38201209, 2023). "SCN10A may be a gene that causes Brugada syndrome, although this has not yet been proven." (PMID 27446933, 2016).
atrial fibrillation (18 papers, 2016 to 2024). A disorder characterized by an electrocardiographic finding of a supraventricular arrhythmia characterized by the replacement of consistent P waves by rapid oscillations or fibrillatory waves that vary in size, shape and timing and are accompanied by an irregular ventricular response. "The nonsynonymous SCN10A single nucleotide polymorphism (SNP) rs6795970 has been reported to associate with PR interval and atrial fibrillation (AF) and in strong linkage disequilibrium (LD) with the AF-associated SNP rs6800541." (PMID 28281580, 2017). "Recent data show that the Nav1.8 channel (SCN10A gene) is a modulator of cardiac conduction, and SCN10A variants have been associated with atrial fibrillation (AF) and BrS." (PMID 37626795, 2023). "Several studies have shown that SCN10A/NaV1.8 is associated with myocardial repolarization and cardiac conduction, as well as atrial fibrillation (AF) and VF." (PMID 34409080, 2021). "Importantly, in vivo experiments in SCN10A−/− mice showed that genetic ablation of NaV1.8 protects against atrial fibrillation induction." (PMID 32078054, 2020).
neuropathy (12 papers, 2013 to 2024). A disorder affecting the nervous system that manifests with pain, tingling, numbness, and/or muscle weakness. "Selective blockade of Nav1.8 function promotes hypoalgesia, gain of function mutations of SCN10A in humans can promote painful neuropathy and its optogenetic silencing in DRG attenuates neuropathic pain." (PMID 35295464, 2021).
small fiber neuropathy (11 papers, 2016 to 2024). "The established role of NaV1.8 in mouse pain has recently been validated by human genetics, as several gain-of-function mutations have been identified in the SCN10A gene that encodes for NaV1.8 in painful small-fiber neuropathy patients." (PMID 37679042, 2023). "The tetrodotoxin-resistant Nav1.8 channel is encoded by the SCN10A gene and different mutations in the SCN10A gene have been observed in small fiber neuropathy in humans." (PMID 34531721, 2021). "Rare missense variants have also been reported in SCN9A and SCN10A in patients with painful small fiber neuropathy." (PMID 32295642, 2020).
epilepsy (9 papers, 2008 to 2025). A brain disorder characterized by episodes of abnormally increased neuronal discharge resulting in transient episodes of sensory or motor neurological dysfunction, or psychic dysfunction. "The association between familial hemiplegic migraine-related genes (CACNA1A, ATP1A2, and SCN1A) and both migraine and epilepsy, as well as the impact of polymorphisms in pain-related sodium channels SCN9A and SCN10A on migraine chronification, have been further elucidated." (PMID 41404467, 2025). "Another group of genes, CHD2, SCN10A, and TBC1D8, was associated with HGF and PTEN; these two genes are related to synaptic plasticity, neuronal cell survival, and CNS development, as well as related to epilepsy." (PMID 33584793, 2020).
melanoma (6 papers, 2020 to 2024). A malignant, usually aggressive tumor composed of atypical, neoplastic melanocytes. "In a melanoma model, Nav1.8-Cre mice, which express Cre only in Nav1.8+ (also known as SCN10A+) sensory neurons, were crossed with mice expressing mutant G protein-coupled receptors that can either induce or inhibit sensory neuron activity." (PMID 36621886, 2023). "To investigate this in more detail, we inoculated a GFP-expressing melanoma (B16F10-eGFP) cell line into Nav1.8cre::tdTomatofl/WT mice (Nav1.8 is also known as Scn10a)." (PMID 36323780, 2022). "Strikingly, the high expression of SCN10A is potentially associated with better SKCM patient survival, indicating that the presence of sensory neurons within melanoma counteracts cancer progression." (PMID 34784974, 2021).
cardiac conduction disease (5 papers, 2012 to 2024). "In particular, they showed that the SCN10A intronic variant rs6801957, identified in a GWAS associated with cardiac conduction disease, is located in an enhancer region that modulates the expression of SCN5A gene." (PMID 33202810, 2020).
channelopathies (5 papers, 2014 to 2023). "In addition, the SCN4A, SCN5A, and SCN10A genes that encode the skeletal muscle NaV1.4, the cardiac NaV1.5 and the PNS NaV1.8 channels, respectively, are associated with other channelopathies." (PMID 36891145, 2023). "Since KSD and SUNDS are associated with channelopathies but the cause of SUNDS in the NE Thai population has not fully been elucidated, it is also interesting to investigate the causal relationship between SUNDS and other mutations of SCN10A." (PMID 29992996, 2018).
Obesity (5 papers, 2015 to 2024). Accumulation of substantial excess body fat. "Only a very small number of above-threshold GWAS loci, including SORT1 for LDL cholesterol, the FTO/IRX3 locus for obesity, and the SCN5A/SCN10A locus for QRS duration, have been investigated in detail." (PMID 27162171, 2016). "In one study conducted on the dorsal root ganglia (DRG), the authors show that LXRs protect Sodium channel 10 alpha subunit (Nav1.8 also called SCN10A) expressing sensory neurons from ER stress and also from mechanical allodynia induced by diet-related obesity." (PMID 31461876, 2019).
primary erythromelalgia (5 papers, 2016 to 2024). "The SCN10A gene encodes the voltage-gated sodium channel alpha subunit and mutations in SCN10A cause Episodic Pain Syndrome, Familial 2, and Sodium Channelopathy-Related Small Fiber Neuropathy." (PMID 32466254, 2020). "Primary erythromelalgia is often caused by mutations in the SCN9A, SCN10A, and SCN11A genes, which encode for NaV1.7, NaV1.8, and NaV1.9, neuronal sodium channels." (PMID 39458034, 2024). "Heterozygous missense mutation in the neuronal voltage-gated sodium channel X alpha subunit (also known as voltage-gated sodium channel subunit alpha Nav1.8) gene, SCN10A, were reported to be the cause of familial episodic pain syndrome-2 (FEPS2;)." (PMID 36140801, 2022).
psoriasis (5 papers, 2017 to 2024). An autoimmune condition characterized by red, well-delineated plaques with silvery scales that are usually on the extensor surfaces and scalp. "In the imiquimod-induced, IL (interleukin)-23-dependent, psoriasis-like skin of mice, SCN10A+ nociceptors interact with DDCs, regulate the IL-23/IL-17 pathway, and control cutaneous immune responses." (PMID 34357026, 2021).